TRIM16 (tripartite motif containing 16)
Diseases named in the same sentence as TRIM16 in open-access papers (continued):
Sharing a sentence is not in itself a finding about the gene and the disease.
melanoma (continued). "In melanoma, we have shown TRIM16 protein expression to be significantly associated with favourable prognosis in stage III melanoma patients, while enforced expression identified TRIM16 as a growth and metastasis suppressor, its effect mediated via IFNβ1 transcriptional activation." (PMID 27447557, 2016). "In addition, TRIM16 expression may potentiate the cytotoxic effect of vemurafenib treatment on BRAFWT melanomas." (PMID 27447557, 2016). "The mechanism by which TRIM16 expression is lost in melanoma cells is presently unknown." (PMID 25333256, 2014). "As combination treatment of vemurafenib and C012 increases TRIM16 protein expression, we investigated the tumor growth rate of engrafted BRAFWT/NRASQ61R melanoma cells, sensitive to the drug combination in vitro, in a xenograft model." (PMID 27447557, 2016). "Overall, our findings have identified a novel small molecule with clinical potential in the treatment of melanoma, including BRAFWT melanoma, and provide mechanistic insights into the role of TRIM16 in this process." (PMID 27447557, 2016). "TRIM16 has been recently identified as a candidate tumor suppressor gene in melanoma and is reactivated by vemurafenib in BRAFV600E melanoma cells." (PMID 27447557, 2016). "However, the role of TRIM16 in melanoma is currently unknown." (PMID 25333256, 2014). "Heterozygous, but not homozygous, TRIM16 knockout mice exhibited an accelerated development of skin papillomas and melanomas, larger melanoma lesions and an increased potential for lymph node metastasis." (PMID 31342168, 2019). "Mechanistically, this combination effect is mediated, in part, by the re-activation of TRIM16 expression, previously shown to be a metastasis suppressor in melanomagenesis that can be restored by vemurafenib in BRAFV600 melanoma in vitro and in patients treated with vemurafenib." (PMID 27447557, 2016). "To evaluate whether induction of TRIM16 expression was necessary for vemurafenib effects on melanoma cell viability we silenced TRIM16 gene expression using two TRIM16-specific siRNA's and treated BRAF-mutant A375 melanoma cells with vemurafenib." (PMID 25333256, 2014). "Interestingly, we found that treatment of melanoma cells with the BRAF inhibitor, vemurafenib, which attenuated ERK phosphorylation, resulted in increased levels of TRIM16 protein in vitro and in vivo." (PMID 25333256, 2014). "It is not clear how TRIM16 expression is lost in melanoma cells." (PMID 33919088, 2021). "TRIM16 is known to be secreted by keratinocytes, but no studies have been reported yet to assess the relationship between TRIM16 keratinocyte expression and melanoma development." (PMID 31342168, 2019).
neuroblastoma (10 papers, 2012 to 2023). Neuroblastoma (NB) is the most common solid, extracranial childhood tumor. "Since TRIM16 has been demonstrated to sensitize cancer cells to retinoids in neuroblastoma and breast cancer cells 15, 16, the loss of endogenous nuclear TRIM16 may be one possible cause of retinoid resistance in skin SCC cells." (PMID 22009481, 2012). "Overexpression of TRIM16 has been shown to decrease neuroblastoma cell growth, cell motility, and tumourigenicity." (PMID 34452557, 2021). "In neuroblastoma, the overexpression of TRIM16 reduces cell growth, cell motility and tumourigenicity." (PMID 34452557, 2021). "In breast cancer and neuroblastoma cells, it has been confirmed that TRIM16 overexpression induces apoptosis through the induction of caspase-2 activity." (PMID 34452557, 2021). "One of TRIM protein, TRIM16, has been demonstrated to acts as a tumour suppressor protein in neuroblastoma via effects on cytoplasmic vimentin and nuclear E2F1." (PMID 31342168, 2019). "Further, the downregulation of vimentin is required for the ability of TRIM16 to inhibit neuroblastoma cell migration." (PMID 31342168, 2019). "Additional work has demonstrated that TRIM16 inhibits neuroblastoma cell proliferation through cell cycle regulation and localization to the nucleus." (PMID 31342168, 2019). "High basal or induced expression of the tripartite motif protein, TRIM16, leads to reduce cell growth and migration of neuroblastoma and skin squamous cell carcinoma cells." (PMID 25333256, 2014). "TRIM16 was identified as a key regulator of the retinoid anti-cancer signal in human neuroblastoma and breast cancer cell lines." (PMID 23404198, 2013). "TRIM16 protein expression in primary tissues from human neuroblastoma and squamous cell carcinoma of skin is decreased in the more malignant phenotype." (PMID 23404198, 2013). "We have previously performed cDNA microarray analysis and found that TRIM16 overexpression resulted in an increase in caspase-2 expression in neuroblastoma cancer cells." (PMID 23404198, 2013). "We demonstrated that overexpressed TRIM16 reduced neuroblastoma cell growth, enhanced retinoid-induced differentiation, and decreased tumourigenicity in vivo." (PMID 22009481, 2012). "The retinoid signalling molecule, tripartite motif protein 16 (TRIM16), is a regulator of keratinocyte differentiation and a tumour suppressor in retinoid-sensitive neuroblastoma." (PMID 22009481, 2012). "Moreover, high levels of TRIM16 has been demonstrated to induce apoptosis in human breast cancer and neuroblastoma cells through the induction of caspase-2 activity." (PMID 34452557, 2021). "TRIM16 is central for the differentiation of neuroblastoma (NB) cells." (PMID 31137886, 2019). "In addition, we have observed that TRIM16 can act as a tumor suppressor in the childhood cancer neuroblastoma, via the binding and down-regulation of cytoplasmic vimentin and nuclear E2F1." (PMID 27447557, 2016). "Several cell cycle regulators, such as PLK1, TRIM16, WEE1, CDK4/6, and CCND1, have been shown to be involved in the tumorigenesis of neuroblastoma." (PMID 26225123, 2015). "TRIM16 exhibits tumour suppressor functions by interacting with cytoplasmic vimentin and nuclear E2F1 proteins in neuroblastoma and squamous cell carcinoma cells, reducing cell migration and replication." (PMID 23404198, 2013). "In addition, TRIM16 down-regulated protein-binding partners, cytoplasmic vimentin and nuclear E2F1, in neuroblastoma cells." (PMID 25333256, 2014). "Here we have shown that TRIM16 upregulates caspase-2 protein levels in breast cancer and neuroblastoma cells but not non-malignant cells." (PMID 23404198, 2013). "Our studies revealed that TRIM16 acts as a tumour suppressor, promoting neuritic differentiation, cell migration, and replication through interactions with cytoplasmic vimentin and nuclear E2F1 in neuroblastoma cells." (PMID 22009481, 2012).
breast carcinoma (8 papers, 2012 to 2023). "In this study, we found that TRIM3 and TRIM16 are both down-regulated in breast cancer, and in addition, our results demonstrated that TRIM3 is highly associated with breast cancer grade." (PMID 36180926, 2022). "In this study, we investigated the expression of TRIM3 and TRIM16 genes in normal and breast cancer tissue samples and compared the expression of the two genes between different clinical and pathological states." (PMID 36180926, 2022). "TRIM3 and TRIM16 genes expression were both positively correlated with the invasion of breast cancer." (PMID 36180926, 2022). "TRIM16 is suggested by Kim as a suppressor factor in breast cancer that reduces the viability of breast cancer cells." (PMID 36180926, 2022). "Regarding the roles of TRIM3 and TRIM16 in breast cancer, a limited number of studies have been conducted, most of which are are in vitro." (PMID 36180926, 2022). "First, TRIM16 can enhance the transcription of retinoic acid receptor β (RARβ), and overexpression of TRIM16 significantly reduces the proliferation of RA-sensitive NB cells as well as RA-resistant lung and breast cancer cells." (PMID 31820796, 2019). "The anti-tumor function of TRIM16 has also been elucidated in many other cancers, such as ovarian cancer, breast cancer, non-small cell lung cancer and melanoma." (PMID 31820796, 2019). "Eventually, we propose TRIM3 and TRIM16 as potential tumor suppressors in terms of breast cancer." (PMID 36180926, 2022). "And the study of Yao, working on the effects of TRIM16 in breast cancer cells and tissue samples, implies that TRIM16 expression is lowered in breast cancer tissues, and that the enzyme inhibits the proliferation and properties of breast cancer stem cells (CSCs)." (PMID 36180926, 2022). "Next, we used six different clinical and pathological parameters, including tumor size, necrosis, histological grade, TNM stage, lymphatic/vascular invasion, and perineural invasion to gain a better view of the effects of TRIM3 and TRIM16 through the progression breast cancer." (PMID 36180926, 2022). "The expression of TRIM3 and TRIM16 are significantly reduced in breast cancer tissues." (PMID 36180926, 2022). "Hence, we suggest a potential tumor suppressor role for TRIM3 and TRIM16 in breast cancer." (PMID 36180926, 2022). "According to such additional filter, six cancer-specific proteins in colon cancer (CEACAM8, CDH17, GLOD5, PPM1E, TRIM16, EPCAM) and one in breast cancer (CCR9) were identified." (PMID 36243758, 2022). "According to such parameters, six cancer-specific proteins in colon cancer (CEACAM8, CDH17, GLOD5, PPM1E, TRIM16, EPCAM), one in breast cancer (CCR9) and none in prostate cancer were identified." (PMID 36243758, 2022).
cardiac hypertrophy (7 papers, 2022 to 2025). "E3 ubiquitin ligase TRIM16 is a critical regulator in cardiovascular pathologies, including myocardial hypertrophy, myocardial ischemia, and reperfusion injury, and exerts either significant cardiovascular protection or pathological change promotion functions." (PMID 41362701, 2025). "They found that TRIM16 deficiency significantly worsened myocardial cell hypertrophy, while TRIM16 overexpression had a beneficial effect, reducing myocardial hypertrophy and remodelling through activation of the downstream Nrf‐2 pathway." (PMID 39192479, 2024). "One study investigated TRIM16's role in pathological myocardial hypertrophy by generating cardiac‐specific TRIM16 knockout mice and AAV9‐TRIM16 transfected mice." (PMID 39192479, 2024). "TRIM16 has recently been identified as a novel suppressor of pathological cardiac hypertrophy, acting through interaction with Prdx1 to inhibit its phosphorylation and thereby activate the Nrf2 pathway, ultimately attenuating cardiomyocyte enlargement and adverse remodeling." (PMID 41362701, 2025). "TRIM16 deficiency significantly exacerbates cardiomyocyte hypertrophy, while overexpression of TRIM16 inhibits cardiac hypertrophy, suggesting that a TRIM16 inhibitor could be a novel inhibitor of pathological heart hypertrophy and heart failure." (PMID 37621776, 2023). "In a chronic kidney disease‐related heart injury model, TRIM16 mediates the ubiquitination and degradation of RIP2, inhibits p38 phosphorylation, and alleviates myocardial hypertrophy and diastolic dysfunction." (PMID 41362701, 2025). "E3 ligases, which determine substrate specificity in ubiquitination, are increasingly recognised for their role in pathological cardiac hypertrophy, with ligases such as TRAF6, TRIM16 and WWP1 being identified as key contributors." (PMID 40753540, 2025). "Also the following tachycardia-specific miR-1183-regulated targets showed a cardiovascular association: the gene NEU3 with cardiac fibrosis and CHD, ZNRD1 with CHD, TRIM16 with cardiac hypertrophy, BIRC3 with ischemic preconditioning, ARRDC3 with cardiac hypertrophy, and MTAP with ischemic stroke." (PMID 35805966, 2022).
chronic obstructive pulmonary disease (3 papers, 2022 to 2024). A chronic and progressive lung disorder characterized by the loss of elasticity of the bronchial tree and the air sacs, destruction of the air sacs wall, thickening of the bronchial wall, and mucous accumulation in the bronchial tree. "In the pathogenesis of chronic obstructive pulmonary disease (COPD), TRIM16 and galectin-3 play a synergistic role in initiating lysosomal membrane permeabilization (LMP) and inducing lysosomal autophagy (a selective lysosomal autophagy process), mediating lysosomal damage." (PMID 36249749, 2022).
lung carcinoma (3 papers, 2012 to 2025). "Characterization of the tumor suppressive role of LncPTEN1 in cancer progression via modulating Trim16 mediated Vimentin degradation provided promising therapeutic target for lung cancer metastasis." (PMID 40521243, 2025). "We have previously shown increased apoptosis of MD-MBA-231 breast and SK-MES-1 lung cancer cells following forced expression of TRIM16." (PMID 23404198, 2013). "We have recently found that TRIM16 overexpression correlated with cell growth inhibition through effects on cyclin D1 and phospho-Rb in lung cancer cells." (PMID 22009481, 2012). "Enforced overexpression of TRIM16 induces apoptosis in MB-MDA-231 breast and SK-MES-1 lung cancer cells, however, the exact mechanisms of TRIM16 involvement in the regulation of apoptosis remains unclear." (PMID 23404198, 2013). "TRIM16 also induces apoptosis in breast and lung cancer cells, by unknown mechanisms." (PMID 23404198, 2013). "In this study, we demonstrated that LncPTEN1 promotes ubiquitination of Vimentin mediated by Trim16 to facilitate Vimentin degradation, thereby inhibiting the EMT process and suppressing lung cancer metastasis." (PMID 40521243, 2025).
lymph node metastasis (3 papers, 2014 to 2020). "The most significant decrease in TRIM16 expression was observed between the dermal invasive melanoma >1mm stage and the lymph node metastasis stage." (PMID 25333256, 2014).
prostate carcinoma (3 papers, 2019 to 2022). A carcinoma that arises from epithelial cells of the prostate gland. "The expression level of TRIM16 in prostate cancer was decreased and associated with patients’ overall survival." (PMID 34452557, 2021). "TRIM16 is also at low levels in prostate tumors and enforced expression of TRIM16 inhibits prostate cancer cell migration and invasion in a manner associated with the inhibition of Snail signaling pathway and EMT process." (PMID 31820796, 2019). "The expression level of TRIM16 in prostate cancer tissues was shown to be lower than normal tissues and was directly linked with patients’ overall survival." (PMID 34452557, 2021). "Other studies on prostate carcinoma and NSCLC, have shown that higher levels of TRIM16 lead to the inhibition of the EMT process and tumor cells invasion." (PMID 34452557, 2021). "It has been confirmed that TRIM16 overexpression inhibits epithelial-to-mesenchymal transition (EMT) process and the invasion of tumor cells in prostate carcinoma and also in non-small cell lung cancer (NSCLC) cells." (PMID 34452557, 2021).
serous ovarian cancer (3 papers, 2023 to 2025). "CRABP2 promotes epithelial mesenchymal transition (EMT) in serous ovarian cancer by upregulating the expression of enhancer of zeste homolog 2 and promoting the methylation of tripartite motif containing 16 (TRIM16)." (PMID 38807101, 2024). "Moreover, CRABP2 had been observed in serous ovarian cancer cells to enhance TRIM16 methylation through upregulation of EZH2, resulting in enhanced EMT effect." (PMID 38186580, 2023). "CRABP2 enhances the methylation of TRIM16 by elevating EZH2 expression, subsequently expediting the epithelial-mesenchymal transition in serous ovarian cancer cells." (PMID 39991584, 2025).
squamous cell carcinoma (3 papers, 2012 to 2019). A carcinoma arising from squamous epithelial cells. "First, we assessed the loss of keratinocyte TRIM16 expression on the development of skin papilloma after carcinogen treatment, as we have previously reported the relationship between TRIM16 loss and progression from normal skin to squamous cell carcinoma." (PMID 31342168, 2019). "Interestingly, 3/30 TRIM16 heterozygous TRIM16+/flox mice developed histologically confirmed squamous cell carcinomas (SCC, red arrow)." (PMID 31342168, 2019).
viral infections (3 papers, 2023 to 2024). "However, the effects of TRIM16 on viral infection have rarely been reported, and it was only found that after infection with HBV virus that the expression of TRIM16 was significantly up-regulated." (PMID 36851605, 2023). "However, it is still possible that TRIM16 could impact viral infections in other ways via modulating antiviral signalling, virus-induced autophagy pathways, and/or production of inflammatory mediators from virus-infected cells." (PMID 37375542, 2023). "TRIM16 and TRIM25 are E3 ubiquitin ligases that play key roles in the host’s immune response to viral infections." (PMID 39211041, 2024). "As our previous RNA-seq studies indicated that TRIM16 expression was upregulated in airway epithelial cells of mice infected with IAV, we hypothesised that it may represent a component of innate immunity to virus infection." (PMID 37375542, 2023).
colon cancer (2 papers, 2022 to 2023). "However, the bioinformatics analysis indicated that TRIM16 was co-related with good prognosis of colon cancer." (PMID 37671092, 2023). "In this study, we evaluated the expression of TRIM16, TRIM22, and TRIM29 in colon cancer." (PMID 37671092, 2023).
gastric cancer (2 papers, 2021 to 2024). A primary or metastatic malignant neoplasm involving the stomach. "To date, few studies have investigated the association between TRIM16 expression and gastric cancer." (PMID 34452557, 2021). "TRIM16, significantly upregulated in tissues from stage IV gastric cancer patients, is directly regulated by the lncRNA SDMGC." (PMID 39768197, 2024). "Previous published studies are limited and unsatisfactory about the role of TRIM16 in gastric cancer." (PMID 34452557, 2021). "In sum, this study suggests a tumor suppressive role for TRIM16 in gastric cancer and proposes it as a potential candidate for GC prognosis." (PMID 34452557, 2021). "Interestingly, TRIM15 and TRIM16 not only show higher expression in gastric cancer tissues, promoting cancer progression, but also exhibit lower expression in some studies, where they inhibited cancer progression." (PMID 39768197, 2024). "However, a positive correlation between TRIM16 expression and gastric cancer (GC) progress has created a controversial situation that need to be fully delineated." (PMID 34452557, 2021). "Interestingly, despite increased levels of TRIM3 and TRIM16 in human gastric cancer tissues, they showed a negative correlation with the β-catenin levels and some of its downstream targets in vitro, such as BCL2, suggesting their tumor-suppressing function." (PMID 39768197, 2024).
lung adenocarcinoma (2 papers, 2023 to 2024). A carcinoma that arises from the lung and is characterized by the presence of malignant glandular epithelial cells. "Trim56 and Trim16 are considered as ubiquitin ligase for vimentin to suppress ovarian cancer and lung adenocarcinoma progression, respectively." (PMID 38383479, 2024). "Moreover, Trim16-dependent vimentin polyubiquitination and degradation was reported in lung adenocarcinoma that was diminished by AKT-induced lncRNA VAL." (PMID 36631457, 2023).
metastatic disease (2 papers, 2012 to 2014). "Among a group of patients with distant metastatic disease, we observed a strong positive correlation between TRIM16 and IFNβ1 levels." (PMID 25333256, 2014).
metastatic melanoma (2 papers, 2014 to 2016). A melanoma that has spread from its primary site to another anatomic site. "Our novel mechanistic insight of the re-activation of TRIM16 in this study provides a basis for further investigation of small molecules that induce TRIM16 for the treatment of metastatic melanoma." (PMID 27447557, 2016).
nonalcoholic steatohepatitis (2 papers, 2022). "Regarding metabolism, Trim16 could ameliorate nonalcoholic steatohepatitis by promoting the degradation of phospho-TAK1." (PMID 35871160, 2022). "Recently, it was reported that TRIM16 was able to mediate the degradation of phospho-TAK1, therefore ameliorating nonalcoholic steatohepatitis." (PMID 36713382, 2022).